NSUN2 (NOP2/Sun RNA methyltransferase 2)
Diseases named in the same sentence as NSUN2 in open-access papers (continued):
Sharing a sentence is not in itself a finding about the gene and the disease.
cancer (continued). "In ESCC patients, NSUN2 promotes cancer development and chemo-resistance via the mRNA-m5C modification of cancer-related genes and enhances their expression, such as TIGAR11 and GRB212." (PMID 38589454, 2024). "ENO1, as the classical enzyme, plays a crucial role in glucose metabolism and cancer development, while high expression of NSUN2 leads to the reprogramming of glucose metabolism via m5C modification of ENO1 in CRC." (PMID 38769664, 2024). "A recent study reported that LRRC8A was upregulated by NSUN2-mediated m5C modification in cancer cells, and m5C-modified LRRC8A mRNA increased RNA stability by binding to YBX1." (PMID 39273558, 2024). "Collectively, our findings validate that NSUN2 operates as an RNA m5C methyltransferase in cancer cells." (PMID 38403250, 2024). "Another m5C writer, NSUN2 (NOL1/NOP2/SUN domain family member 2), exhibits high expression in different cancer types and plays a significant role in cancer progression regulation." (PMID 38201505, 2023). "To further investigate the impact of TIAM2 on NSUN2-induced cancer progression, we co-transfected siRNA (siTIAM2 or siCtrl) into vector control or NSUN2-overexpressing PC cells." (PMID 37393317, 2023). "As a critical RNA m5C catalytic enzyme, the functions of NSUN2 have been described in multiple types of cancer." (PMID 36183976, 2023). "NOP2/Sun RNA methyltransferase 2 (NSUN2), an important methyltransferase of m5C, has been poorly studied in cancers, and the relationship between NSUN2 and immunity remains largely unclear." (PMID 37769000, 2023). "NSUN2, a major m5C mRNA methyltransferase, has been found overexpressed and activated in many types of cancer including LUAD." (PMID 36123390, 2023). "The TIMER, CPTAC and other databases were used to analyze the expression of NSUN2, its correlation with clinical stage and its prognostic value across cancers." (PMID 37769000, 2023). "Overall, these previous studies have identified NSUN2 as an oncogene in many cancers, whose main function is to stabilize target mRNA or to promote export and translation of the target mRNA." (PMID 36792587, 2023). "Pan-cancer analysis showed that NSUN2 is positively correlated with DNA copy number and mRNA expression, which are associated with poor prognosis." (PMID 36183976, 2023). "Different candidate genes related to ATC progression were then selected to verify the NSUN2's role in promoting cancer‐related translation." (PMID 37983928, 2023). "NSUN2 serves as a pan-cancer prognostic biomarker and is correlated with the immune infiltration of tumors." (PMID 37769000, 2023). "Apart from cancers, NSUN2-mediated m5C can regulate adipogenesis by promoting CDKN1A mRNA export and translation." (PMID 36792587, 2023). "NSUN2, an RNA methyltransferase, has been reported to be highly expressed in pan-cancer and displays different clinical values in various cancers." (PMID 37047493, 2023). "High levels of NSUN2, another m5C methyltransferase, have been found in several different cancer types, but the functional role of NSUN2 in regulating proliferation was not clear." (PMID 35350378, 2022). "In the Cancer Genome Atlas (TCGA) pan‐cancer result, NSUN2 was the only poor outcome predictor of overall survival (OS) in PCa." (PMID 36169095, 2022). "Currently, studies regarding the regulation of NSUN2 in terms of biological function and cancer mechanism focus on its modification of mRNA." (PMID 35562754, 2022). "In bladder cancer, the m5C modification writer NSUN2 was shown to promote cancer development by regulating HDGF expression in an m5C modification-dependent manner." (PMID 35433474, 2022). "Two kinds of m7G tRNA modifying enzymes, METTL1 and NSUN2, determine 5-Fluorouracil (a drug used in the treatment of cancer) sensitivity in human cancer cells." (PMID 36118897, 2022). "The NSUN2 and METTL1 tRNA modification genes have been associated with resistance to anti-cancer therapy." (PMID 35721477, 2022).
cancer (continued). "NSUN2 is responsible for the majority of mRNA:m5C in mammalian cells and is upregulated in various cancer types." (PMID 33922187, 2021). "NSUN2-mediated m5C deposition in tRNAs regulates differentiation and stress responses in tissue and in cancer stem cells." (PMID 33461542, 2021). "RNA m5C modification is catalyzed by several methyltransferases, among which, NSUN2 has attracted increasing attentions because of its oncogenic role in various types of cancers." (PMID 34345012, 2021). "IHC showed that NSUN2 was expressed mainly in the nucleus of cancer cells, and partially expressed in the cytoplasm." (PMID 34504059, 2021). "In gastric cancer, NSUN2 acts as an oncogene to repress p57Kip2 in an m5C-dependent manner, which in turn, contributes to the development of cancer." (PMID 33928086, 2021). "Unexpectedly, deletion of NSun2 in mouse cells and mouse cancer cells led to hypomethylated tRNAs which showed to be more vulnerable to the ribonuclease angiogenin, and consequently to the accumulation of 5′-tRNA fragments." (PMID 33461542, 2021). "For instance, NSUN2 targets the 3' untranslated region and stabilizes the mRNA of heparin binding growth factor, which regulates cancer progression." (PMID 34512153, 2021). "KEGG analysis showed that NSUN2-mediated m5C-modified genes were significantly enriched in multiple cancer-related signaling pathways, such as the Rap1 signaling pathway, platinum drug resistance, and the regulation of cell cycle processes." (PMID 34504059, 2021). "A subset analysis of The Cancer Genome Atlas (TCGA) datasets confirms that the expression of NSUN2 is frequently overexpressed at the mRNA level in various cancers, as are various other members of the m5C RNMTs." (PMID 32708015, 2020). "Because different types of cancer possess distinct contexts and NSUN2 can target multiple RNAs simultaneously, it is likely that NSUN2 exerts its pleiotropic roles in a context-dependent pattern." (PMID 32101138, 2020). "In their study of Proteinase activated-receptor 2 (PAR2)-mediated cancer cell migration, Wang and colleagues identified NSUN2 as a critical protein in this process." (PMID 32708015, 2020). "The RNA methyltransferase NSUN2 has been involved in the cell proliferation and senescence, and is upregulated in various types of cancers." (PMID 32332707, 2020). "However, the role of NSUN2 in cancers and the mechanisms underlying are largely unknown." (PMID 33093178, 2020). "There were a few reports on the elevated expression of NSUN2 in a range of cancer, including oral, head and neck, colorectal, breast, ovarian, and GI cancers, which was consistent with our bioinformatics analysis." (PMID 33365328, 2020). "In other words, if NSUN2 predominantly targets oncogenic RNA molecules in specific types of cancer, it would function as an oncogene." (PMID 32101138, 2020). "Conversely, NSUN2 knockdown markedly reduced the proliferation, migration, and invasion of cancer cells in vitro, and tumorigenicity in vivo." (PMID 27447970, 2017). "Previous studies suggest an alternative mechanism by which NSUN2 overexpression contributes to cancer development." (PMID 25233213, 2014). "The upregulated expression of NSUN2 in cancer cells is notable because the overexpression is accompanied by gene copy number gain." (PMID 25233213, 2014). "In HCC, the overexpression of NSUN2 in cancer cells augments this process." (PMID 41522342, 2026). "Therefore, NSUN2 regulates the m5C modification of tRNA, affects codon-specific translation, and thereby regulates cancer progression and drug resistance." (PMID 41501031, 2026). "NSUN2 is a tRNA modification enzyme that affects codon-specific translation by regulating the m5C modification of tRNA, thereby regulating the occurrence and development of cancer." (PMID 41501031, 2026). "However, NSUN2 upregulation in prostate cancer cells decreased the responsiveness of cancer cells to 5-fluorouracil treatment." (PMID 41522342, 2026).
cancer (continued). "In addition, NSUN2 plays important roles in various cancers, such as esophageal cancer, liver cancer, gastric cancer, ovarian cancer, and head and neck squamous cell carcinoma, by affecting tRNA modification and may become a valuable target for cancer treatment and a diagnostic marker for cancer." (PMID 41501031, 2026). "•NAA10 catalyzes lactylation of NSUN2 rendering cancer cell ferroptosis resistant." (PMID 39742570, 2025). "NSUN2, a cytosine methyltransferase, is a well-studied m5C writer in cancer." (PMID 41301491, 2025). "In addition, the aberrant m5C modification mediated by NSUN2 in PC is associated with the upregulated expression of TIAM2 mRNA, which promotes EMT and the likelihood of cancer cell migration." (PMID 40860147, 2025). "Functional assays confirmed that these compounds effectively suppressed the catalytic activity of recombinant NSUN2 without affecting NSUN6, and stereoselectively disrupted the interaction between NSUN2 and tRNA in cancer cells, leading to a global reduction of tRNA m5C levels." (PMID 41256859, 2025). "Research indicates that NSUN2 is closely involved in regulating angiogenesis in cancer cells." (PMID 41413017, 2025). "As GCLC-catalyzed GSH synthesis plays a key role in redox homeostasis and ferroptosis sensitivity, we further evaluated whether NSUN2 lactylation regulates GCLC-dependent sensitivity to ferroptosis in cancer cells." (PMID 39742570, 2025). "Additionally, lncRNAs have been shown to influence the degradation of methyltransferases like NSUN2, thereby affecting m5C modification of target mRNAs and facilitating cancer metastasis." (PMID 40234937, 2025). "NSUN2 increases the expression of target genes by promoting m5C modification in various cancers." (PMID 40713894, 2025). "Additionally, when developing drugs targeting NSUN2 in cancer therapy, future efforts should focus not only on blocking its RNA modification pathways but should also consider its m5C‐independent functions." (PMID 40156167, 2025). "Third, NSUN2 expressions were various in several cancer types." (PMID 40657390, 2025). "Notably, NSUN7 has the least foundational research on cancer progression with only two studies, whereas NSUN2 has been the most extensively studied." (PMID 41462962, 2025). "Taken together, our findings suggest that NSUN2 is essential for mediating ferroptosis resistance in OSCC and that its inhibition could increase the susceptibility of cancer cells to the induction of ferroptosis." (PMID 41436732, 2025). "A substantial body of evidence indicates that NSUN2 is highly expressed in multiple cancer types." (PMID 38403250, 2024). "Although NSUN2 was confirmed to play an important role in various cancers in later extensive studies, it has been shown that tRNA methylation modifications may have a wide and significant impact on drug resistance in cancer cells." (PMID 39019857, 2024). "Since the primary cause of death in cancer is often metastasis and deregulation of cell migration during cancer progression can determine the potential of cancer cells to invade adjacent tissues and form metastases, we assessed the effect of NSUN2 on NSCLC cell migration and invasion." (PMID 38403250, 2024). "Notably, NSUN2 has garnered increased attention due to its carcinogenic role in various cancer types." (PMID 39595099, 2024). "In the case of m5C, the level of m5C is closely related to carcinogenesis, and NSUN2 could promote cancer cell proliferation via up-regulating the m5C levels." (PMID 38589454, 2024). "Hence, the CRC syngeneic mouse model was employed to further assess the efficacy of NSUN2 inhibitor in combination with PD‐1 blockades, and the encouraging results supported the potential ability of NSUN2 for cancer immunotherapy in CRC." (PMID 38769664, 2024). "Targeting NSUN2 exhibited broad anti‐cancer effects in vitro and in vivo." (PMID 37983928, 2023).
cancer (continued). "The top 1000 genes with decreased TE enriched in several cancer‐related pathways, including metabolism of RNA, translation, regulation of cellular response to stress and VEGFA–VEGFR signalling pathway, suggesting the role of NSUN2 in a crucial pro‐cancer program." (PMID 37983928, 2023). "In addition, high NSUN2 expression was associated with a poor prognosis in LIHC, KIRC, LUAD and other cancer types." (PMID 37769000, 2023). "Considering the crucial role of EMT in cancer metastasis, we further investigated whether NSUN2 expression affected EMT." (PMID 37393317, 2023). "Since NSUN2‐mediated m5C RNA modification is an important trigger of purine synthesis, our study bridges the current knowledge of m5C modification and metabolic reprogramming in cancer." (PMID 37228185, 2023). "For instance, NSUN2-mediated methylation of tRNAs regulates the generation of 5’tRFs, which in turn activate stress signalling, induce proteostatic stress, and ultimately decrease the functionality and stress sensitivity of stem and cancer stem cells." (PMID 37660182, 2023). "Therefore, the purpose of this study was to explore the expression and prognostic value of NSUN2 and the role of NSUN2 in immunity in cancers." (PMID 37769000, 2023). "Considered for the cancer-promoting effect and an essential role in m5C modification, we focused on NSUN2, which might mediate the regulation of DIAPH2-AS1 on the expression of NTN1." (PMID 37037818, 2023). "METTL1 and NSUN2, determine 5-Fluorouracil sensitivity in human cancer cells." (PMID 36118897, 2022). "In addition, as in other cancers, NSUN2 also played a cancer-promoting effect in BRC, promoting BRC cell proliferation in vitro and in vivo and cell migration and invasion in vitro." (PMID 35484099, 2022). "Both revealed the cancer-promoting role of m5C writer NSUN2 in ESCC." (PMID 35484099, 2022). "However, little is known about how aberrantly expressed NSUN2 contributes to pathogenesis and development of cancer." (PMID 35280737, 2022). "Notably, most current studies focus on mRNA, but the modification of rRNA by NSUN5 and the modification of lncRNA and miRNA by NSUN2 suggest the potential of m5C modification of non-coding RNA for cancer development." (PMID 35562754, 2022). "m5C methyltransferases, especially NSUN2, regulates substrate levels by catalyzing m5C modification of target RNA to mediate the crosslinking of a series of oncogenic or antitumor factors, thus affecting tumorigenesis and cancer progression." (PMID 35562754, 2022). "Through regulation by NSUN2, m5C modifications were shown to be involved in the onset of various cancers, and may be potential targets for cancer treatment." (PMID 35721510, 2022). "These cellular context and epigenetic differences may lead to the varying roles of NSUN2 in these cancers." (PMID 35280737, 2022). "According to TCGA data, we found that NSUN2 was overexpressed in various cancers; thus, we speculated that NSUN2 might act as a common oncogene that participates in human cancer progression." (PMID 34504059, 2021). "Collectively, these findings indicate that the NSUN2 gene may be involved in important biological processes in cancer tumorigenesis." (PMID 33928086, 2021). "The relationship between NSUN2 and SUMOylation within the context of cancer progression and metastasis remains unclear." (PMID 34504059, 2021). "However, very little is known about the precise regulatory mechanism of NSUN2-mediated mRNA m5C modification in human diseases, especially human cancer." (PMID 34345012, 2021). "By modifying the gene sequence of key RNA m5C methylases, such as NSUN2, reduced RNA methylation may prevent the occurrence of disease or reverse cancer progression." (PMID 34512153, 2021).
cancer (continued). "More recently, another report showed that in cancer cells NSUN2 aberrant methylation of oncogenic mRNAs at the 3′ UTR increased their interaction with the reader protein Y-box-binding protein 1 (YBX1), which maintained the stability of its targeted mRNAs by recruiting ELAVL1." (PMID 33461542, 2021). "Collectively, these results indicate that NSUN2 levels are closely related to the migration and invasion properties of GC cells; hence, NSUN2 may act as a pan-cancer oncogene." (PMID 34504059, 2021). "Perturbations of a number of tRNA modifications and altered expression of the corresponding modifying enzymes such as TRMT12, NSUN2, or DNMT2, have been linked to numerous human diseases, including cancer, neurological disorders, and mitochondrial-linked disorders." (PMID 32290274, 2020). "Over the following sections, we describe the emerging data regarding the role of NSUN2 in cancer." (PMID 32708015, 2020). "Finally, a very recent study has identified a role for NSUN2 in gastric cancer promoting cancer cell proliferation both in vitro and in vivo via repression of the cyclin dependent kinase p57Kip2 in an m5C-dependent manner." (PMID 32708015, 2020). "This NSun2-ATX regulatory process affects cancer cell migration." (PMID 33093178, 2020). "NSUN2 (NOP2/Sun domain family member 2; MYC induced SUN domain-containing protein, Misu) is a RNA methyltransferase implicated in cell proliferation, stem cell differentiation, testis differentiation, and human cancer." (PMID 27447970, 2017). "To examine the effects of double knockdown of NSUN2 and METTL1 on further chemotherapeutic agents other than 5-FU, we used cisplatin, a platinum-containing anti-cancer drug that binds to and causes crosslinking of DNA, and paclitaxel, a microtubule-stabilizing mitotic inhibitor." (PMID 25233213, 2014). "Although the elucidation of the roles of NSUN2 overexpression in cancer cells is still challenging, mitotic spindle-related NSUN2 functions involved in chromosome segregation processes might induce chromosome instability leading to cancer progression." (PMID 25233213, 2014). "Furthermore, elevated NSUN2 expression correlates with diminished responsiveness to chemotherapy and attenuated immune cell infiltration, highlighting the multifaceted impact of NSUN2 in cancer." (PMID 40008496, 2025). "Our analysis suggests that NSUN2 may function as a pan-cancer promoter in humans." (PMID 41462962, 2025). "Moreover, NSUN2 maintains the drug resistance of cancer cells to chemotherapy drugs." (PMID 40463874, 2025). "Therefore, NSUN2 rs13181449-associated lower expression might decrease the activation of the cell cycle and PI3K-AKT pathway, protecting cancer development more obviously for patients with cigarette smoking." (PMID 40657390, 2025). "Thinking of the dynamic and reversible nature of RNA methylation, it is likely that NSUN2 activity is actively regulated by lactate-mediated lactylation, which then modulates the m5C level and stability of target genes eventually facilitating cancer cell survival under acidic TME condition." (PMID 39742570, 2025). "However, whether NSUN2 function is regulated by lactylation which further affects ferroptotic resistance phenotype in cancer cells is still unclear." (PMID 39742570, 2025). "Furthermore, m5C-Bis-Seq and mRNA-Seq analyses identified LAMC2 as a potential target regulated by NSUN2 in promoting EMT in HNSCC, providing novel insights into how NSUN2 modulates the m5C landscape and facilitates cancer progression through the stabilization of LAMC2 mRNA." (PMID 39595099, 2024). "Moreover, an effective small‐molecule inhibitor of NSUN2 has been indentified in diminishing the enzymatic function and the expression of downstream targets, offering a novel and promising therapeutic option in the realm of cancer immunotherapy for CRC." (PMID 38769664, 2024).